OR51A2 (olfactory receptor family 51 subfamily A member 2)
Description:
Odorant receptor.
Tractability: Antibody: UniProt places it where antibodies can reach, with medium confidence; UniProt predicts a signal peptide or a membrane-spanning region; its Gene Ontology location is reachable by antibodies, with medium confidence.
Gene: Protein-coding gene on chromosome 11 (4,954,772 to 4,955,713, reverse strand). Ensembl gene ENSG00000205496.
Subcellular location: Cell membrane
Pathways (Reactome):
Sensory Perception: Expression and translocation of olfactory receptors
Gene Ontology:
Molecular function: olfactory receptor activity; G protein-coupled receptor activity; signaling receptor activity
Biological process: cellular response to lipid; detection of chemical stimulus involved in sensory perception of smell; G protein-coupled receptor signaling pathway; system process
Cellular component: plasma membrane; membrane
Genetic constraint (gnomAD): Missense variants: 84 observed, 193.29 expected, observed/expected ratio (o/e) 0.43, 90% interval 0.36 to 0.52. Synonymous variants: 48 observed, 79.24 expected, observed/expected ratio (o/e) 0.61, 90% interval 0.48 to 0.77.
Homologues: Orthologues: macaque OR51A4 (92% identical), dog OR51A4 (86% identical), tropical clawed frog or51ao1 (45% identical). Paralogues in human: OR51A4 (97% identical), OR51A7 (70% identical), OR51G2 (58% identical), OR51G1 (54% identical), OR51L1 (52% identical), OR51Q1 (50% identical), OR51E1 (49% identical), OR51C1 (48% identical), OR51E2 (48% identical), OR51I2 (48% identical), OR51F2 (47% identical), OR51V1 (46% identical), and 39 more.